ERBB2 (erb-b2 receptor tyrosine kinase 2)
Diseases named in the same sentence as ERBB2 in open-access papers (continued):
Sharing a sentence is not in itself a finding about the gene and the disease.
breast tumors (continued). "Clinicopathological parameters of ERBB2-overexpressing ductal breast tumors and nuclear KLF6." (PMID 20126619, 2010). "Although a cannabinoid-based monotherapy might be potentially effective for ErbB2-positive breast tumors, it would be interesting to analyze the effect of these compounds in combination with other anticancer treatments." (PMID 20649976, 2010). "We first analyzed whether ErbB2-positive human breast tumors express cannabinoid targets (i.e. cannabinoid receptors)." (PMID 20649976, 2010). "As expected, breast tumor cell lines typically expressed much higher levels of ERBB2 mRNA." (PMID 21318160, 2010). "Although overexpression of erbB3 alone may induce mammary carcinogenesis, overexpression of both erbB2 and erbB3 has been observed frequently in a transgenic mouse model that overexpresses the wild-type erbB2 protein, and in human breast tumor samples." (PMID 19590682, 2009). "Breast tumours have been classified into five molecular subtypes; basal, luminal A, luminal B, ERBB2 and normal-like by identifying a set of genes with significantly greater variation in expression between different tumours than between paired samples from the same tumour." (PMID 18803878, 2008). "Therefore, elucidating the mechanisms leading to ERBB2 gene overexpression is an important step in understanding the pathogenesis of a particularly aggressive subset of breast tumors." (PMID 18218085, 2008). "Thus, the ErbB2/ErbB3 dimer functions as an oncogenic unit to drive breast tumor cell proliferation." (PMID 19384426, 2007). "The 80 breast tumor samples were assigned to five different subgroups according to their gene expression pattern; luminal A, highly proliferating luminals, normal-like, basal-like and ERBB2+." (PMID 17504517, 2007). "Moreover, expression of ISGF3G and MxA was inversely correlated with ErbB-2 expression in the panel of breast tumour cell lines." (PMID 14710226, 2004). "However, another study has demonstrated that endogenous PPARγ1 could promote ErbB2-mediated breast tumor occurrence and development." (PMID 36902342, 2023). "Indeed, genetic ablation of PTP1B delays ErbB2 breast tumour progression and metastasis." (PMID 28436416, 2017). "In addition to morphological profiling, immunohistochemical analyses for specific markers—including estrogen receptor (ERα), progesterone receptor (PR), and human epidermal growth factor receptor 2 (HER2/NEU/ERBB2)—have allowed breast tumors to be classified into different subtypes." (PMID 27110512, 2016). "In addition, NR3B1 activates transcription of the genes contained in the ERBB2 amplicon observed in the majority of HER2+ breast tumors, possibly explaining the delay in tumor development observed following NR3b1 knock-out in a mouse model of ERBB2-initiated mammary cancerogenesis." (PMID 26894976, 2016). "In addition, about one third of breast tumors with amplified PPM1D locus also contain amplification of the ERBB2/HER2 oncogene suggesting that both genes may jointly promote tumor development." (PMID 26883108, 2016). "Our findings indicate that the induction of PTK6 in ERBB2-induced tumors is physiologically significant, and suggest that targeting PTK6 in ERBB2-positive breast tumors could restrain several signaling pathways that have critical roles in ERBB2-induced tumorigenesis." (PMID 26247733, 2015). "For example, breast tumors are commonly assessed for three receptors that are used as pathological biomarkers: the presence or absence of estrogen receptor (ER) and progesterone receptor (PR), and the enrichment of human epidermal growth factor receptor 2 (HER2 or ERBB2)." (PMID 25541715, 2014).
breast tumors (continued). "Interestingly, the greater percentage of metastatic (positive) lymph nodes occurred in patients with ERBB2 overexpressing ductal breast tumors showing in addition positive nuclear stain for KLF6 (88%, 7/8), and represent the major subpopulation of cases with analyzed axillary lymph nodes." (PMID 20126619, 2010). "Here we conducted a retrospective study to determine whether the amplicon pattern, including amplification or deletion of TOP2A correlates with clinico-pathologic characteristics of breast tumors, markers of proliferation, and the clinical outcome of patients with ERBB2-amplified BC." (PMID 18702822, 2008). "In addition, most basal-like or ErbB2-overexpressing breast tumours do not present the same clinical characteristics associated with IBC." (PMID 17848951, 2007). "We conducted a literature search for studies reporting differences in HER2-positive breast tumor prevalence among populations and HER2/ERBB2 molecular features based on genomic background or ancestry." (PMID 40777119, 2025). "Positive correlation of ERRα with ERBB2/HER2 mRNA levels and amplified in breast cancer-1 (AIB1) protein levels were observed in breast tumors." (PMID 35178385, 2022). "Patient data support this conclusion where breast tumors with decreased expression of FOXA1 were less proliferative, had reduced ERBB2/ERBB3 (HER2/HER3) expression, and increased enrichment of immune signatures." (PMID 34680352, 2021). "In breast tumors from cohort 1, higher VMP1 expression level was observed in ERBB2/HER2 positive tumors based on classification with immunohistochemistry (HER2, p = 7x10-4) or molecular subtyping (p = 5x10-6, )." (PMID 31442252, 2019). "In different subtypes of patient breast tumor tissues, tissue expressing high ErbB2 have less expression of the autophagy proteins LC3A, LC3B, and Beclin 1 compared to tissues expressing low ErbB2." (PMID 28338617, 2017). "In breast tumour cells expressing activated ErbB-2, treatment with TGF-β results in a striking increase in cell motility compared to cells expressing mutant inactive ErbB-2." (PMID 30210578, 2017). "This EphA2-mediated amplification of ErbB2 signalling contributes to breast tumour initiation and metastasis in mouse mammary tumour virus (MMTV)-ErbB2/Neu transgenic mice." (PMID 27619642, 2016). "Our study demonstrates that gasdermin B (GSDMB), mapped 175 kilo bases distal to ERBB2, is amplified and over-expressed in a subset (~60%) of HER2-positive breast tumours." (PMID 27462779, 2016). "One of the most significant partnerships of MYC in both breast and uterus cancer cells involves ERBB2, whose effect on the over-expression of the TF in HER2+ breast tumors has been noted before." (PMID 26792175, 2016). "In the clinic, breast tumors are routinely classified based on the presence of the estrogen and progesterone receptors (ER/PR) and HER2/NEU (also known as ERBB2), as expression of these receptors has immediate therapeutic implications." (PMID 25699542, 2015). "Cyclin D1 is overexpressed in the majority of human breast tumors, many of these representing downstream effects through induction of cyclin D1 by oncogenic signals (Ras, MAPK), Src, ErbB2, STATs, Notch, NFκB." (PMID 25940700, 2015). "By contrast, CB2 immunoreactivity was detected in 72% of human breast tumor tissue and 91% of ErbB2-positive tumor tissue, suggesting a link between CB2 and ErbB2-expression." (PMID 25115386, 2014).
breast tumors (continued). "Further analysis of the levels of ErbB2 transcripts by quantitative real-time RT-PCR in MMTV-PyVT/HdhQ7/Q7 and MMTV-PyVT/HdhQ111/Q111 breast tumours confirmed this observation." (PMID 23300147, 2013). "The combination inhibitions COX-2+ERBB2 and COX-2+ERBB3 can exceptionally exert little effect on the metastasis for breast tumor, which are reflected by the ~ 98% remaining metastasis after inhibition." (PMID 23967306, 2013). "TGFα, whose overexpression drives the breast tumors in the mouse model studied here, is closely related to EGF and an activating ligand for the proto-oncogene Her2, also called Neu or ErbB-2, a member of the EGFR family." (PMID 24279986, 2013). "Targeting ADAM-17 metalloproteinase activity has been recently described as a new alternative to treat breast tumors through inhibition of particular EGFR ligands and ERBB2 shedding." (PMID 23028451, 2012). "Correlation between ErbB-2 nuclear presence and COX-2 expression in breast tumor specimens has already been reported." (PMID 22356700, 2012). "Knowledge of hormone receptor and ERBB2 status as well as the global gene expression profiles of breast tumor samples may permit more accurate prognostic tests to be developed and would strengthen the value of the many breast tumor gene expression profiles in public depositories." (PMID 22022496, 2011). "We sought to determine the preclinical benefit of combining a Notch inhibitor (γ-secretase inhibitor (GSI)) and trastuzumab in both trastuzumab-sensitive and trastuzumab-resistant, ErbB-2-positive, BT474 breast tumours in vivo." (PMID 21847123, 2011). "More importantly, seventy-one percent (15/21) of the ductal breast tumor tissues sub-population with both nuclear KLF6 distribution and ERBB2-overexpression also were positive for Estrogen Receptor alpha." (PMID 20126619, 2010). "We have previously shown that proliferation of the estrogen-receptor-positive MCF7 and T47D, and the ErbB2-overexpressing JIMT-1, SKBR3 and BT474 breast tumor cell lines is decreased following treatment with sFRP1." (PMID 19473496, 2009). "ERBB2, AP-2α, and YY1 protein levels were analyzed by immunohistochemistry in a panel of 55 primary breast tumors." (PMID 18218085, 2008). "For ERBB2, amplification is the predominant method of its up-regulation and is the basis for FISH-based tests evaluating the ERBB2 status of breast tumors." (PMID 17584934, 2007). "Clusters of genes containing some of the most important known markers of breast tumour phenotype are shown in greater detail: ESR1, MKI67, ERBB2, and TFF1." (PMID 17555561, 2007). "The classification of the breast tumour into the different cell-of-origin subtypes was validated using IHC for ER, PR, ErbB2, EGFR and CK5/6 using a TMA containing core biopsies of each breast tumour in our gene-expression data set." (PMID 17848951, 2007). "Breast tumours belonging to these subclasses more often demonstrate respectively EGFR and ErbB2 overexpression." (PMID 17700572, 2007). "Our results from the cellular thermal shift assay (CETSA) showed that the addition of 3oc did not affect the thermal stability of either TβRII or ErbB2, suggesting that 3oc did not engage with these proteins in breast tumor cells." (PMID 39786928, 2025). "The Erbb2 mice with hetSrsf3 KO showed intermediate outcome in overall tumor formation, and mice without Erbb2 failed in breast tumor induction during 18 months of observation period." (PMID 40568073, 2025). "Additionally, another study demonstrated that ErbB2 inhibits the upregulation of BLNK by reducing the levels of the tumor cell transcription factor IRF6, thus facilitating breast tumor growth." (PMID 39596658, 2024). "Only 62 transcripts were commonly upregulated in breast tumours against both healthy breast and non-breast tissues, featuring ERBB2, ERBB3, EPCAM, and IGFR." (PMID 38306344, 2024).
breast tumors (continued). "Breast tumors are commonly classified into four subtypes based on the expression of estrogen receptor (ER), progesterone receptor (PR), and human epidermal growth factor receptor 2 (HER2/ERBB2)." (PMID 38468288, 2024). "Basal breast tumors, characterized by their lack of estrogen and progesterone receptors while maintaining normal Her2 (ERBB2) levels, are another major clinical subtype." (PMID 39741968, 2024). "For example, some ERBB2+ and mutant PIK3CA breast tumors show elevated RHOC expression." (PMID 38807216, 2024). "Indeed, transgenic mice overexpressing NCAPH generated breast tumors with long latency, and in MMTV-NCAPH/ErbB2+ double-transgenic mice, the luminal tumors formed were more aggressive." (PMID 37886490, 2023). "For example, ERBB2 and ERBB1 dimerize with the same affinity as the ERBB1 homodimer, and overexpression of ERBB2 and its heterodimerization with ERBB3 are both essential to induce breast tumor cell proliferation." (PMID 37219601, 2023). "Based upon immunohistochemical staining for key proteins’ expression, breast tumors are considered to contain at least 1% of the following genes: human epidermal growth factor receptor 2 (HER2, Erbb2 gene), estrogen receptor (ER), and progesterone receptor (PR, Pgr gene)." (PMID 37153758, 2023). "Remarkably, when evaluating ErbB2 in breast tumors separated to ErbB2-amplified and non-amplified, the RNA-protein correlation of amplified tumors is 0.86, while the RNA-protein correlation of non-amplified tumors is only 0.26." (PMID 37290530, 2023). "In ErbB2-negative breast tumor cell lines, Notch3-mediated signaling was shown to play an important part in the proliferation." (PMID 36017236, 2022). "Intriguingly, p50/RelA heterodimer was documented to be related in nearly 86% of estrogen receptor (ER)-negative and Her2/ErbB2-positive breast tumors." (PMID 36422540, 2022). "Then, survival analysis was made across all genes and the best performing genes were ranked for two cohorts with high clinical relevance: ER positive ERBB2 negative patients who received chemotherapy and basal breast tumors with chemotherapy." (PMID 34527184, 2021). "The Human Epidermal Growth Factor Receptor 2 (HER2)-amplified subtype is characterized by the amplification and overexpression of the v-erb-b2 avian erythroblastic leukemia viral oncogene homolog 2 (ERBB2) gene and represents ~20% of breast tumours." (PMID 34572926, 2021). "Based on the expression of estrogen receptor (ER), progesterone receptor (PgR), and ERBB2 (HER2), breast tumors are classified as luminal A, luminal B, HER2, and basal-like or triple-negative (TNBC), which exhibit different tumor aggressiveness and response to therapy." (PMID 33230261, 2021). "In primary breast tumors, high CPNE3 RNA levers significantly correlate with ERBB2 amplification." (PMID 35003348, 2021). "In contrast, trastuzumab failed to upregulate PERP in EVs emitted by ErbB2-positive trastuzumab-resistant human breast tumor cells HCC-1419." (PMID 33023655, 2020). "The ERBB2/ERBB3 heterodimer functions as an oncogenic unit that drives tumorigenesis; for instance, ERBB3 phosphorylation is increased in many ERBB2-overexpressing breast tumors." (PMID 31752936, 2019). "Patients whose breast tumors overexpress the ErbB2 have a significantly lower survival rate and a shorter period before relapse than patients without ErbB2 overexpression." (PMID 30241301, 2018). "Compared with the frequency of ErbB2 overexpression (25%–30%), the high frequency of PTK6 expression (60%–86%) in breast tumor cells suggests that this protein has great potential as a new therapeutic target, especially in patients with no ErbB2 expression." (PMID 27311570, 2016). "Also in the human HER2+ breast tumour cell line BT474, in which ERBB2 is amplified, Irs4 expression had a strong effect on anchorage independent growth (P=0.0143, Welch's t-test)." (PMID 27876799, 2016).
breast tumors (continued). "Particularly SHARPIN which was highly expressed in metastatic (Supplementary S3) and ERBB2 negative breast tumors." (PMID 26506596, 2015). "Similar results were obtained by Tramm and colleagues who showed that the surrounding non-neoplastic tissue does not affect the quantification of ESR1, PGR, and ERBB2 mRNA expression in breast tumor samples." (PMID 25218890, 2014). "However, GIANT successfully identified amplification on chromosome 17 that harbored ERBB2 (HER2) oncogene, indicating this breast tumor was HER2-positive." (PMID 24498045, 2014). "Malignant breast tumors are classified in the ER/PR positive types Luminal A (ERBB2 negative) and Luminal B (ERBB2 positive) and the ER/PR negative types: basal-like, ERBB2 positive, and normal-like." (PMID 24098698, 2013). "Consistent with the diagnoses with FISH, ERBB2 copy number remained low in 10 ERBB2-negative (by FISH) breast tumors." (PMID 23181561, 2012). "For example, in studies of breast tumors it may be important to determine the expression level of the genes ESR1 and ERBB2, which correspond to the clinically important estrogen receptor (ER) and Her2 proteins." (PMID 22172014, 2011). "If the putative non-functional protein plays a role in ERBB2-driven breast tumor remains to be addressed." (PMID 21731642, 2011). "Despite this oncogene being most extensively investigated in clinical and basic oncology, the ERBB2-mediated mechanism involved in the transformation and progression of breast tumors has not yet been totally elucidated." (PMID 21210970, 2010). "ERBB2 overexpressing ductal breast tumors did not revealed a preferential relationship of histological grades and nuclear KLF6 expression." (PMID 20126619, 2010). "Cluster 4 is enriched with triple negative tumors (ER, PR and ERBB2 negative) (71% or 32/45, Pvalue < 4.74e-8), while Cluster 3 has similar receptor positivity as the remaining breast tumors in Cluster A." (PMID 20017941, 2009). "Proliferation genes were also expressed at higher levels in the ERBB2 overexpressing breast tumors relative to ERBB2-negative tumors." (PMID 18631401, 2008). "TOP2A aberrations (amplification or deletions) occur in less than 10% of ERBB2 non-amplified breast tumors." (PMID 18702822, 2008). "In contrast, no tumors examined were markedly positive for ErbB2, a well-known mammary oncogene that is often amplified and overexpressed in human breast tumors." (PMID 18808719, 2008). "For the breast tumours classified as basal-like tumours, 5 out of 7 had no ER, PR or ErbB2 overexpression (‘triple negative’), whereas only 4 out of 52 non-basal-like breast tumours were triple negative (Pearson χ2, P<0.0001)." (PMID 17848951, 2007). "Out of 19 ER+ breast tumours 15 showed no overexpression of EGFR and/or ErbB2 whereas 10 out of 18 ER− breast tumours showed overexpression of EGFR and/or ErbB2 (κ=−0.343, P=0.031)." (PMID 17700572, 2007). "Rather, it appears that a HER2 amplification event was followed by clonal selection for broad regions around ERBB2 and other loci within each amplicon, consistent with the observation of clonally heterogeneous HER2 amplifications in primary breast tumors by whole-genome sequencing." (PMID 39946483, 2025). "Lapatinib inhibited Walker 256 rat breast tumour cell proliferation but with lower cytotoxic effect, which could be due to lower ErbB2 mRNA with ErbB1 mRNA was not able to be detected in the cells." (PMID 31905843, 2019). "Breast tumors expressing estrogen receptor, but not ERBB2, more frequently give bone metastasis." (PMID 24731990, 2014). "Additionally, Notch3 promotes proliferation and inhibits apoptosis of ErbB2-negative breast tumor cells via activation of the CSL (CBF-1/RBP-Jκ, Su(H) and Lag-1) pathway." (PMID 23426998, 2013).